STAT1 (signal transducer and activator of transcription 1)
Diseases named in the same sentence as STAT1 in open-access papers (continued):
Sharing a sentence is not in itself a finding about the gene and the disease.
colon carcinoma (continued). "Colon cancer patients with high STAT1 expression have better clinical outcomes than those with low STAT1 expression in the colon tissue." (PMID 34299314, 2021). "Mechanism investigations indicated that SARI down‐regulates p‐STAT1 and STAT1 expression in colon cancer cells, following inhibition of MCP‐1/CCR2 axis activation during CAC development." (PMID 31578820, 2020). "STAT1 has a complex role during tumourigenesis, and it has been proposed to link intestinal inflammation and colon cancer by its involvement in crosstalk between stromal and epithelial cell populations." (PMID 30538296, 2019). "Combination of MG with GLOI silencing exerts synergistic inhibitory effects on colon tumorigenesis and colon cancer growth mediated through up-regulation of STAT1 and Bax and down-regulation of Bcl-2." (PMID 28903386, 2017). "In this study, we investigated the anticancer effects of MG alone or in combination with silencing of GLOI and their potential underlying molecular mechanisms, particularly with involvement of STAT1 pathway in colon cancer using cell lines and an animal model." (PMID 28903386, 2017). "STAT1 protein levels were increased in all four types of colon cancer cells after treatment with MG (0.4 or 0.8 mmol/L) or GLOI silencing." (PMID 28903386, 2017). "In another murine model of colon cancer, however, intestinal polyp formation was equal in animals carrying a STAT1 deletion compared with STAT1-expressing mice, and SOCS1 has also been proposed as an oncogene mediating its effect through STAT1-downregulation." (PMID 26938566, 2016). "Here, it seems to have a protective function as normal intestinal fibroblasts, but not activated fibroblasts or fibroblasts from patients with IBD, activate STAT1 in colon cancer cells and thereby inhibit the growth of the tumor cells." (PMID 26938566, 2016). "We show that normal fibroblasts inhibit proliferation of colon cancer cells and that myofibroblasts isolated from a CD patient, which fail to induce STAT1 signaling in tumor cells, lack this inhibitory activity." (PMID 24818101, 2014). "It has also been demonstrated that miR-145 targets MUC1 in metastatic breast cancer, p70S6K1 in colon cancer, c-Myc in non-small cell lung cancer and the transcription factor STAT1 in colon cancer." (PMID 25277192, 2014). "In this study, we show that normal fibroblasts induce STAT1 signaling and restrain the growth of colon cancer cells." (PMID 24818101, 2014). "Case-control studies, using more than 1550 patients with colon cancer and 750 cases of rectal cancer, demonstrated that JAK2, SOCS2, STAT1, STAT3, STAT5A, STAT5B, and STAT6 were associated with colon cancer, and that STAT3, STAT4, STAT6, and TYK2 were linked to rectal cancer." (PMID 36982677, 2023). "Additionally, it has been reported that STAT1 promotes apoptosis and suppresses the proliferation in colon tumor cells." (PMID 34299314, 2021). "In colon cancer cells, overexpression of miR-145-5p reduced STAT1 expression." (PMID 27765924, 2016). "As expected, Ruxolitinib blocked IFNγ mediated STAT1 activation in human colon carcinoma cells." (PMID 26497740, 2015). "We showed that myofibroblasts isolated from CD or UC patients, who are at increased risk of developing colon cancer, were not able to induce STAT1 in carcinoma cells and failed to inhibit their growth." (PMID 24818101, 2014). "Finally, we confirmed that silencing of STAT1 in tumor cells alters the crosstalk between tumor cells and fibroblasts, suggesting STAT1 as a novel link between intestinal inflammation and colon cancer." (PMID 24818101, 2014). "We have identified a number of miR-145 targets that could be interesting in a cancer context and verified that miR-145 targets YES and STAT1 in colon cancer cells." (PMID 20098684, 2010). "However, the role of STAT1 during inflammation-associated colon cancer has not been well stablished." (PMID 30235866, 2018).
colon carcinoma (continued). "However, high levels of STAT1 expression and activation in mucosal samples have been observed in patients with UC and CD which may account for accelerated colon cancer development." (PMID 30235866, 2018). "A positive correlation between STAT1, IRF2 and PD-1 is observed in the myeloid cells in human colon cancer patients." (PMID 38995014, 2024). "Butyrate reduced JAK2 phosphorylation, JAK1 phosphorylation, STAT1 phosphorylation and its nuclear translocation and DNA binding activity in IFN-γ-activated HCT116 or Hke-3 colon carcinoma cell lines." (PMID 35409339, 2022). "Nuclear STAT1 was directly targeted and inhibited by SARI in colon cancer cells, which mediated the inhibition of MCP‐1 expression by SARI." (PMID 31578820, 2020). "Treatment of the colon cancer cell line Colo 205 and the TNBC cell line with inhibitor 4 resulted in decreased STAT1 phosphorylation (pSTAT1), indicating inhibition of CDK8 in all these cell lines, as expected." (PMID 33291686, 2020). "STAT1 is involved in defense against pathogens and the inhibition of cell proliferation in SW480 colon cancer cell." (PMID 28903386, 2017). "Onnis et al43 showed that IL-11 activates an oncogenic signalling pathway, through STAT1 and 3, that increased anchorage-independent growth in prostate cancer PC3, colon cancer HCT116, and renal cancer RCC4 cells." (PMID 27384883, 2016). "To establish the mechanism whereby normal intestinal fibroblasts regulate the growth of colon cancer cells, we transfected HCT116 cells with reporter genes measuring the activity of major signaling pathways, including AP1, NFκB, Wnt, and STAT1." (PMID 24818101, 2014). "To investigate the specific inhibition of GO-Y030, we detected the phosphorylation of STAT3, STAT1, or STAT6 induced by IL-6, IFN-γ, or IL-4 in HT29 colon cancer cell lines." (PMID 21694723, 2011). "In colon cancer, oncogenic K-ras inhibits the expression of IFN-responsive genes through inhibition of STAT1 and STAT2 expression." (PMID 18506145, 2008). "Importantly, two natural alkaloids, berberine (BER) and coptisine (COP), compete with STAT1 for binding to BLM-G4, thereby significantly suppressing BLM expression in colon cancer cells." (PMID 42087785, 2026). "In vitro experiments shows that Zharp1-211 was highly potent for blocking TNF-induced necroptosis in human colon cancer HT-29 cells and mouse fibroblast L929 cells, and reduced IFN-γ–induced STAT1 activation in mouse intestinal crypt cells by effecting JAK1/STAT1 pathway." (PMID 40007541, 2025). "Indeed, in colon cancer cells, KLF4 was recently identified as one of the downstream targets of IFNγ and STAT1, mediated through interaction of STAT1 with a GAS element present in the KLF4 promoter." (PMID 41155497, 2025). "Additionally, PCIF1 has been reported to regulate colon cancer growth and response to anti-PD-1 by stabilizing cancer-promoting gene mRNAs, such as FOS, IFITM3, and STAT1, through m6Am modifications." (PMID 39451207, 2024). "NAP, in addition to inhibiting STAT3, may also inhibit STAT1, thereby inhibiting the expression of CD44, and the stemness of colon cancer." (PMID 36732759, 2023). "Furthermore, significant positive correlations of CBX4 with STAT1 and IL-6R/STAT3 were observed, and the activation of STAT1 and IL-6/STAT3 signaling has been reported to promote immunosuppression in the TME of colon cancer." (PMID 34222240, 2021). "Here, we demonstrated that the absence of STAT1 promotes IL-17 activity during the early stages of colon cancer via STAT3 and that IL-17 neutralization prevented tumor growth." (PMID 34299314, 2021). "Although the correlation between proteasome and colon cancer were studied earlier, the detailed interactions between proteasome and STAT1 for mCRC was not addressed before, and thus we would emphasize our research on this mechanism." (PMID 34758826, 2021).
colon carcinoma (continued). "It was demonstrated that histone deacetylases as well as c-Myc, STAT1 and STAT3 may contribute independently to the transcriptional suppression of TMEFF2 in colon cancer, prostate cancer and gastric cancer." (PMID 33663520, 2021). "Further, a study on patients with inborn mutations in their STAT1 genes, and of the potential cross-regulation mechanisms between STAT1 and STAT3, may provide novel therapeutic strategies against colon cancer." (PMID 34299314, 2021). "Further histological examination suggested that there is inverse correlation between SARI and p‐STAT1 level, which is frequently up‐regulated in colon tumour tissues from patients, whereas SARI mRNA expression was positively correlated with STAT1 mRNA expression." (PMID 31578820, 2020). "STAT1 protein expression varied greatly in colon cancer samples, with levels ranging from negative or barely detectable to very high expression." (PMID 32275681, 2020). "In this study we have used comparative gene expression analysis and promoter mapping to demonstrate a direct link between IL-6 and MMP expression in colon cancer, via STAT-1 and novel non-canonical SBEs identified in the MMP-1 and MMP-3 proximal promoters." (PMID 28819304, 2017). "Our results suggest that STAT1, Bax, and Bcl-2 could be involved in the antiproliferative and pro-apoptotic effects of MG and silencing of GLOI in colon cancer cells." (PMID 28903386, 2017). "Moreover, recent work documented that activation of STAT1 and STAT3 correlated with a better prognosis for colon cancer patients." (PMID 24833526, 2014). "Based on the differences found, new hpdODNs were designed and tested for their STAT3/STAT1 discrimination ability by measuring SW480 colon carcinoma cell death and absence of inhibition of STAT1-dependent IFNγ-induced cell death." (PMID 22423663, 2012). "However, although all the tested colon cancer cell lines were responsive to IFN-γ, as revealed by induction of ISGs14, 15 such as STAT-1, STAT-3, interferon responsive factor (IRF-1), and BCLXL, unexpectedly MMP-1 mRNA levels were reduced following IFN-γ treatment (18 h)." (PMID 28819304, 2017). "Activation of STAT1 transcriptional activity by 18Co cells was cell-type specific, as we published before that macrophages failed to modulate STAT1 transcriptional activity in colon cancer cells (data not shown)." (PMID 24818101, 2014). "In an in vitro study, ectopic expression of SARI inhibited p‐STAT1 and STAT1 levels, but had no observed effect on STAT3 and NF‐κB expressions in colon cancer cells." (PMID 31578820, 2020). "Immunoprecipitation and western blotting showed that SARI specifically interacts with STAT1, but not STAT3 and NF‐κB in colon cancer cells." (PMID 31578820, 2020).
Immunodeficiency (62 papers, 2006 to 2026). Failure of the immune system to protect the body adequately from infection, due to the absence or insufficiency of some component process or substance. "Dysregulated STAT-1 signaling is associated with chronic inflammation, tissue damage, and immune dysfunction." (PMID 39376880, 2024). "The immune responses of our STAT1 GOF patient illustrated the complexity of STAT1- associated immunodeficiency, which needs additional research." (PMID 36891307, 2023). "Biallelic STAT1 loss of function (LOF) variants lead to STAT1 deficiency with a severe phenotype of immunodeficiency with increased frequency of infections and poor outcome if untreated." (PMID 37377976, 2023). "Herein, we describe a newborn with novel homozygous variants in both SGPL1 and STAT1 presenting with severe combined immune deficiency and additional clinical features." (PMID 37377976, 2023). "Clinical manifestations in patients with STAT1 mutation, in addition to immunodeficiency includes inflammatory and autoimmune phenomena such as hypothyroidism (22%), type 1 diabetes (4%), blood cytopenia (4%), and SLE (2%)." (PMID 31362757, 2019). "Atypical STAT1 activation leads to cardiovascular diseases like atherosclerosis, whereas STAT1 deficiency is responsible for causing infections and immune disorders." (PMID 25710482, 2015). "In the context of the JAK/STAT pathway, WES allows for the discovery of rare or de novo mutations in coding regions of genes such as JAK1-3, TYK2, and STAT1-6, which may be implicated in immunodeficiencies, autoimmune syndromes, or hematological disorders." (PMID 41438753, 2025). "STAT1 protein has a crucial role in regulating immune responses to viral, fungal, and mycobacterial pathogens, and its mutation has been associated with pathological immunodeficiency." (PMID 37445763, 2023). "The diseases associated with STAT1 include immunodeficiency 31B and immunodeficiency 31C." (PMID 36072011, 2022). "We propose that such models may enhance our understanding of this intricate immune disorder, as well as genotype–phenotype correlation among various STAT1 GOF mutations." (PMID 33990617, 2021). "Our data are consistent with the hypotheses that a shift from a parallel to an antiparallel dimer conformation of STAT1 is required for the termination of IFNγ-mediated gene expression and that a defect in this transition causes human immunodeficiency." (PMID 23922848, 2013). "Mutations of Stat1 cause severe immune deficiencies in humans and mice." (PMID 22719255, 2012). "This complication might be attributed to immune disorders caused by STAT1 GOF." (PMID 36105803, 2022). "Mutations in 6 genes (IL12RB1, CYBB, IFNGR1, IL2RG, STAT1, and RAG1) account for 66% of BCG-associated immunodeficiency mutations." (PMID 41748971, 2026). "Immunodeficiency was present in 37.5% of cases, most commonly hyper-IgE syndrome (HIES)/Job syndrome (28%), followed by STAT1/STAT3 mutations, juvenile idiopathic arthritis, asthma, DAVID syndrome, diffuse proliferative glomerulonephritis, and ALL." (PMID 41149903, 2025). "STAT1 GOF mutations with CMC were first described in 2001 and 2011, respectively; later, studies confirmed that STAT1-GOF mutations cause immunodeficiency and immune dysregulation, with a wide clinical spectrum." (PMID 40149454, 2025). "Our literature search identified 259 new reports of STAT1 GOF immunodeficiency, combining with the Toubiana cohort to yield 533 unique patients from 36 different countries with a confirmed molecular diagnosis of STAT1 GOF." (PMID 41394881, 2025). "The RIG-I/STAT1 signaling pathway is involved in the inflammatory response and immune disorders, and can be activated during an IAV infection." (PMID 40431640, 2025). "Different etiological examinations (for viral, bacterial, immunodeficiency, hyper IgE syndrome, gene mutations) revealed extremely high CMV antigenemia and a homozygous mutation in the STAT1 gene." (PMID 38918745, 2024).
Immunodeficiency (continued). "The STAT1 deficiency can abolish STAT1-dependent cellular response to both INF-α and -γ resulting in immunodeficiency." (PMID 39553536, 2024). "According to the OMIM (Online Mendelian Inheritance in Man) database, ISG15, IRF9, and STAT1 are related to immunodeficiency." (PMID 38113079, 2023). "We report novel homozygous SGPL1 and STAT1 variants in a newborn of Gambian ethnicity with clinical features of SPLIS and severe combined immunodeficiency." (PMID 37377976, 2023). "STAT1 (OMIM: 600555) known to cause dominant or recessive immunodeficiency, was also correctly linked to Severe combined immunodeficiency, with dominant MOI (HGF score: 10.38)." (PMID 32271766, 2020). "Preliminary evidence for this premise is supported by reports of PML cases with mutations in IUIS immunodeficiency disorder genes, such as DOCK8 and STAT1 plus others." (PMID 32256442, 2020). "Gain-of-function (GOF) mutations in the signal transducer and activator of transcription 1 (STAT1) result in unbalanced STAT signaling and cause immune dysregulation and immunodeficiency." (PMID 26604104, 2016). "This is compatible with our earlier findings using STAT-1−/− chimeras, wherein we observed that loss of IFN response in the stromal compartment alone accounted for the immune deficiency to SeV." (PMID 20107606, 2010). "A study of primary immune deficiency cases involving disseminated coccidioidomycosis found two patients had STAT3 LOF mutations, one had IFN-γ receptor-1 deficiency, three had IL-12 receptor LOF mutations, and two had STAT1 GOF mutations." (PMID 41164159, 2025). "MiR-410-5p competitive silencing of STAT1 can avoid macrophage immune disorders." (PMID 38178171, 2024). "Similar dualities for the STAT1 (M600555), TNFRSF13B (M6049097), and TICAM1 (M607601) genes may apply since the first two are associated with immunodeficiency disorders and the last confers susceptibility to encephalopathy from herpes virus infection." (PMID 37504295, 2023). "The most frequently reported monogenic immunodeficiency disease that causes IC and CNSC is Caspase Recruitment Domain Family Member 9 (CARD9) defects, followed by Autoimmune Regulator (AIRE), Signal Transducer And Activator Of Transcription 1 (STAT1), STAT3, and Interleukin 17F (IL17F) defects." (PMID 36526986, 2022). "The significant overlap with STAT1 TFBSs could thus serve as a starting point for functional work looking to understand the role of immune disorders in ASD and psychiatric phenotypes generally." (PMID 29066808, 2017). "Similarly, other mutations such as Y640F in STAT1 or D661V in STAT3, which occur in the SH2 domain or in regions that regulate dimerization, have been reported to enhance STAT activity and are sometimes found in hematologic malignancies and immune disorders." (PMID 41438753, 2025). "Understanding the biochemical and structural details of STAT1 dephosphorylation therefore is required for understanding the physiological regulation of IFNγ signaling as well as for the development of therapeutic STAT1 modulators, e.g., for viral and immune diseases." (PMID 23582260, 2013). "Serine/threonine phosphorylation of STAT1, STAT3 and STAT5 has been shown to contribute to the etiology of certain human cancers and immunodeficiencies." (PMID 35163491, 2022). "Their high correlation to assays targeting STAT1 or ATAD5, which are important in cancer and immune disorders, is a valuable finding by a simple linear correlation analysis of MolData benchmark for drug repurposing." (PMID 35255958, 2022). "Exome sequencing revealed two homozygous hypomorphic mutations affecting the pseudo-kinase domain of JAK1 leading to impaired phosphorylation of several STAT proteins (STAT1, STAT3, STAT4, STAT5, and STAT6), which contributed to the immunodeficiency manifested by the patient." (PMID 41438753, 2025).
Immunodeficiency (continued). "Upon exposure to aerosolized WT-EBOV, BALB/c, C57BL/6 (B6), and DBA/2 (D2) mice were unaffected, but 100% of severe combined immunodeficiency (SCID) and 90% of signal transducers and activators of transcription (Stat1) knock-out (KO) mice became moribund between 7–9 days post-exposure (dpe)." (PMID 23207275, 2012). "These issues may be related to immunodeficiency in AIGA syndrome patients; additionally, previous findings showed that macrophage dysfunction, the inhibition of STAT1 phosphorylation and IL-12 production, and Th1 cell immune injury, can cause microbial clearance failure." (PMID 38497717, 2024). "We found multiple genes with ClinVar variants from patients with primary immune deficiencies (for example, IRF9, IRF7, STAT1, STAT2) that are not GWAS-linked genes but are in their network vicinity, providing evidence of the importance of this gene module for these diseases." (PMID 36823319, 2023).